KMT2D (lysine methyltransferase 2D)
Diseases named in the same sentence as KMT2D in open-access papers (continued):
Sharing a sentence is not in itself a finding about the gene and the disease.
colorectal cancer (9 papers, 2016 to 2026). A primary or metastatic malignant neoplasm that affects the colon or rectum. "The author also observed that in colorectal cancer samples, KMT2D mutations co-occur more frequently than expected with BRAF mutations." (PMID 36275468, 2022). "Notably, our findings contrast with prior reports in lung and colorectal cancers, where KMT2D mutations often coexist with high TMB or MSI." (PMID 40895533, 2025). "Moreover, KMT2D is critical for mediating the survival of activation-induced naïve CD8+T cells, and KMT2D variants in colorectal cancer have been linked to increased CD8+T cells, more immune cell infiltration, and enrichment of immune-related genes and pathways." (PMID 39139573, 2024).
esophageal squamous cell carcinoma (8 papers, 2019 to 2024). Esophageal squamous cell carcinoma (ESCC) is a type of esophageal carcinoma (EC) that can affect any part of the esophagus, but is usually located in the upper or middle third. "Esophageal squamous cell carcinoma cases in the NC group were highly significantly associated with the presence of significantly mutated genes (SMGs) including KMT2D, FAT1, and NOTCH1 mutations." (PMID 36741715, 2022). "KMT2D mutations have been associated with the development of different tumors, including small cell lung cancer, esophageal squamous cell carcinoma, and large B-cell lymphoma." (PMID 30990809, 2019). "KMT2D overexpression was observed in esophageal squamous cell carcinoma (ESCC), predicting poor clinical outcomes and facilitating ESCC tumor progression." (PMID 32164600, 2020). "It has been shown that the expression level of KMT2D may change the prognosis of some cancers, including non-small cell lung cancer and esophageal squamous cell carcinoma." (PMID 38791111, 2024).
acute myeloid leukemia (7 papers, 2020 to 2024). Acute myeloid leukemia (AML) is a group of neoplasms arising from precursor cells committed to the myeloid cell-line differentiation. "KMT2D is identified as a tumor suppressor gene in acute myeloid leukemia." (PMID 37142882, 2023). "It is reported that KMT2D plays a role in the development of acute myeloid leukemia." (PMID 35058979, 2022). "KMT2C and KMT2D function as tumor suppressors in many cancers such as renal cell carcinoma, acute myeloid leukemia (AML), lung adenocarcinoma, and MB." (PMID 39765675, 2024). "According to this result, KMT2D’s expression in a lot of cancers has changed significantly, KMT2D is significantly upregulated in Acute myeloid leukemia (AML)." (PMID 39867575, 2024). "KO-539 induces complete remission (CR) in two out of six patients with relapsed/refractory acute myeloid leukemia (R/R AML), including a minimal residual disease (MRD)-negative CR in a NPM1-mutated AML patient co-mutated for DNMT3A and KMT2D." (PMID 38255885, 2024).
congenital heart disease (7 papers, 2013 to 2026). A heart disease that is present at birth. "Our results provide some clues for KS caused by KMT2D gene mutations associated with congenital heart disease, hearing abnormalities, and hypoglycemia." (PMID 39678395, 2024). "However, the exact function of KMT2D as a human cardiac regulatory gene and its role in specific congenital heart disease development are not fully understood." (PMID 39678395, 2024). "Mutations in histone modifiers KMT2D (histone-lysine N-methyltransferase 2D) and KDM6A (lysine-specific demethylase 6A) and EHMT1 (euchromatic histone-lysine N-methyltransferase 1) have also been associated with syndromic congenital heart disease due to defects in NCC development." (PMID 35108221, 2022).
metastatic tumors (7 papers, 2016 to 2025). "The study identified high frequencies of mutations in genes such as KMT2D (46.4% in primary and 33.3% in metastatic tumors) and JAK1 (31.9% in primary and 28.3% in metastatic tumors)." (PMID 39590142, 2024). "Similarly, distinct mutational patterns emerged between primary and metastatic tumors, with DMD and KMT2D more prevalent in primary tumors, while SAMD9L and ATP8B1 were found in metastases." (PMID 41590495, 2025). "Notably, we observed that KMT2D, also known as MLL2, mutated in close to half of MMR-d primary tumors and in 1/3 of MMR-d metastatic tumors." (PMID 36675550, 2023). "Single nucleotide variant (SNV) frequencies of 34 candidate genes (including KMT2D (46.4%), ZFHX3 (33.3%), JAK1 (31.9%), and RNF43 (27.5%)) and 16 candidate genes (including KMT2D (33.3%) and JAK1 (28.3%)) were higher in MMR-d primary tumors and MMR-d metastatic tumors, respectively." (PMID 36675550, 2023). "For metastatic tumors from GENIE, a total of sixteen candidate genes had significantly higher SNV frequencies in MMR-d tumors, of which six genes (KMT2D (33.3%), JAK1 (28.3%), FAT1 (21.7%), ERBB4 (20.0%), KMT2A (20.0%), and MGA (20.0%)) had a SNV frequency ≥ 20% in MMR-d tumors." (PMID 36675550, 2023). "Driver gene aberrations occurring exclusively in CSF cfDNA and not shared with primary/metastatic tumour or plasma cfDNA (where sequenced) were found in genes involved in histone modification (KAT6B, KMT2D, NUTM2A) and microtubule formation (PDE4DIP)." (PMID 37973922, 2023).
cervical carcinoma (6 papers, 2021 to 2025). A carcinoma arising from either the exocervical squamous epithelium or the endocervical glandular epithelium. "In addition, our study firstly revealed the somatic mutations of KMT2D, NAV3 and PKHD1L1 in cervical cancer, to our knowledge." (PMID 36076209, 2022). "Indeed, the PIK3CA gene is described as the top altered gene in cervical carcinoma along with the MTOR, KMT2D and FAT1 genes." (PMID 36010253, 2022).
CHARGE syndrome (6 papers, 2016 to 2023). CHARGE syndrome is a multiple congenital anomaly syndrome characterized by the variable combination of multiple anomalies, mainly Coloboma; Choanal atresia/stenosis; Cranial nerve dysfunction; Characteristic ear anomalies (known as the major 4 C's). "Therefore, molecular testing of KMT2D should be considered in patients clinically diagnosed with CHARGE syndrome without CHD7 mutations." (PMID 29321794, 2017).
colon carcinoma (6 papers, 2016 to 2022). "In particular, histone-lysine N-methyltransferase genes KMT2D, KMT2C and KMT2B in bladder, lung and endometrial cancers, whereas the KMT2A is mostly mutated in non-small cell lung cancer and colon cancer." (PMID 34302033, 2021). "One study demonstrated that KMT2D promoted global H3K4 monomethylation in transcriptional enhancers, and depletion of KMT2D in two colon cancer cell lines (HCT116 and DLD-1) decreased cancer cell proliferation and migration." (PMID 29925347, 2018).
endometrial cancer (5 papers, 2019 to 2023). Primary or metastatic malignant neoplasm involving the endometrium (mucous membrane that lines the endometrial cavity).
lung adenocarcinoma (5 papers, 2020 to 2026). A carcinoma that arises from the lung and is characterized by the presence of malignant glandular epithelial cells. "To ask if KMT2D also regulates GR expression in non-lymphoid malignancies, we examined A549 lung adenocarcinoma cells, which are known to be GC-sensitive." (PMID 39025450, 2024).
small cell lung carcinoma (5 papers, 2019 to 2024). Small cell lung cancer (SCLC) is a highly aggressive malignant neoplasm, accounting for 10-15% of lung cancer cases, characterized byrapid growth, and early metastasis. "Alterations such as KMT2D deficiency in chromatin organization have been identified as a favorable prognostic marker in small cell lung cancer, and its potential role to enhance the activity of antitumor treatment in pancreatic adenocarcinoma has been shown." (PMID 34885165, 2021). "In addition, KMT2D mutations have also been observed to have a longer survival time in patients with small-cell lung cancer." (PMID 35281840, 2022).
urothelial carcinoma (5 papers, 2021 to 2025). A malignant neoplasm derived from the transitional epithelium of the urinary tract (urinary bladder, ureter, urethra, or renal pelvis). "Erdafitinib, an FGFR inhibitor, is approved for FGFR3-altered urothelial carcinoma, and emerging agents targeting epigenetic alterations such as ARID1A or KMT2D mutations may expand future treatment options." (PMID 41395625, 2025).
angiosarcoma (4 papers, 2021 to 2025). A malignant tumor arising from the endothelial cells of the blood vessels. "In angiosarcomas, the most frequently mutated genes in all three cohorts were KDR, PIK3CA, and NF1, followed by KMT2D, NRAS, and PLCG1, which were among the top 10 genes in two of the three cohorts." (PMID 37568749, 2023). "Although the functionality of these mutations has not been fully clarified, mutations in SRGAP3 and KMT2D have been detected and considered relevant in a variety of sarcomas, including angiosarcoma, endometrial stromal sarcoma and alveolar rhabdomyosarcoma." (PMID 34885165, 2021).
Hypoglycemia (4 papers, 2020 to 2026). A decreased concentration of glucose in the blood. "In this paper, we report a case of KS with neonatal hypoglycemia and special features caused by KMT2D gene mutation confirmed by whole exome sequencing, it enriched the clinical phenotype spectrum and gene mutation spectrum of KS, which helps to improve the understanding of the disease." (PMID 38115267, 2023). "Hyperinsulinemic hypoglycemia was confirmed with glucagon test and whole-exome sequencing (WES) found a novel heterozygous splicing-site mutation (c.674-1G > A) in KMT2D gene." (PMID 32948218, 2020).
oral cancer (4 papers, 2022 to 2024). "From the results, we found that the most commonly mutated gene in the cohort is a histone methyltransferase KMT2D (54.55%), implicating that aberrance in epigenetic regulation may play a role in oral cancer tumorigenesis." (PMID 38477073, 2024). "Additionally, KMT2D has widespread functions as a histone methyltransferase, and other mechanisms that regulate the self-renewal of oral cancer stem cells and promote the progression of OSCC are imperative for further illuminated." (PMID 35477537, 2022).
overnutrition (4 papers, 2021 to 2025). An imbalanced nutritional status resulting from excessive intake of nutrients. "For example, the histone H3 lysine 4 methyltransferase MLL4/KMT2D regulates overnutrition-induced murine steatosis by adding H3K4me1 at PPARγ2 binding sites, a key regulator of hepatic steatosis." (PMID 40862085, 2025). "In a murine MAFLD model, overnutrition contributes to hepatic steatosis by facilitating H3K4 methylation via H3K4 methyltransferase MLL4/KMT2D at steatotic target genes of PPARγ2 and activating their transcription." (PMID 34887768, 2021). "The histone H3 lysine 4 methyltransferase, MLL4 (also called KMT2D), is a critical epigenetic transcriptional coactivator that mediates overnutrition-induced steatosis in mice, but its potential role in the progression of NASH remains largely unknown." (PMID 39542242, 2024).
steatosis (4 papers, 2018 to 2025). Increased lipid within the cytoplasm of cells. "The histone H3 lysine 4 methyltransferase, Mll4/Kmt2d, directs overnutrition-induced murine steatosis via its coactivator function for PPARγ2, whereby overnutrition activates Abl1 kinase which phosphorylates PPARγ2, and hence has enhanced interaction with Mll4." (PMID 30283300, 2018).
gastric adenocarcinoma (3 papers, 2024 to 2026). "Furthermore, mutations in KMT2D, ERBB2/3, and RNF43 are also observed in both G-EAC and gastric adenocarcinoma." (PMID 40432921, 2025). "Based on the observation that loss-of-function mutations of KMT2C and KMT2D (KMT2C/D) are enriched and co-occur in gastric adenocarcinoma, we developed genetically engineered mouse model (GEMM) to conditionally knock out Kmt2c and Kmt2d in gastric epithelial cells." (PMID 42118591, 2026).
head and neck squamous cell carcinoma (3 papers, 2022 to 2025). A squamous cell carcinoma that arises from any of the following anatomic sites: lip and oral cavity, nasal cavity, paranasal sinuses, pharynx, larynx, and salivary glands. "Histone lysine methyltransferase 2D (KMT2D) is the most frequently mutated epigenetic modifier in head and neck squamous cell carcinoma (HNSCC)." (PMID 39117659, 2024). "The Cancer Genome Atlas Network (TCGA) revealed that the mutation frequency of KMT2D in head and neck squamous cell carcinoma (HNSCC) was 18% among 279 HNSCC patients." (PMID 35477537, 2022). "Also, in head and neck squamous cell carcinoma (HNSCC), KMT2D was identified as a tumor suppressor gene promoting cell growth through increasing glycolysis." (PMID 41035915, 2025).
hepatocellular carcinoma (3 papers, 2021 to 2026). A malignant tumor that arises from hepatocytes. "KMT2D has been shown to be mutated in hepatocellular carcinoma cases, and has even been suggested to be associated with earlier recurrence of disease, greater microvascular invasion and a more aggressive phenotype." (PMID 33805950, 2021). "KMT2D has been found to be somatically mutated in hepatocellular carcinoma (HCC) and has also been confirmed as a hepatitis B virus integration site." (PMID 33805950, 2021).
immune deficiencies (3 papers, 2020 to 2024). "KS1-associated immune deficiency (KSAID) can be partially explained through the known role of KMT2D in B-cell survival/cell cycle regulation, differentiation, and peripheral tissue homing." (PMID 38765012, 2024). "Since no diagnostic details are given, the exclusion of combined immune deficiencies involving T-cell immunity as well as B-cell failure, or known mutations in monogenic disease (e.g. CTLA4, LRBA, KMT2D, XIAP, RAG1, NFKB1) is unclear." (PMID 33329602, 2020).
myeloma (3 papers, 2024 to 2025). "Our mutation profile (ARID1A, KMT2D, BCL7A, PTPN11, NUP214) and high CNV load converge with patterns reported across extramedullary/myeloma cohorts, notably MAPK pathway lesions and 1q amplifications." (PMID 41378284, 2025). "Despite the distinct burden of subclonal mutations, some CH mutations were conservative among MM, AL, POEMS, and MGUS, including lymphoid and myeloid CH mutations, such as those in KMT2D, FAT1, MGA, and SYNE1, and myeloma driver genes like ZFHX3 and DIS3." (PMID 40152254, 2025). "To assess if endogenous KMT2D regulates the expression of endogenous GR in these cells, we used CRISPR/Cas9 to target KMT2D in L363 cells, a GC-sensitive multiple myeloma cell line." (PMID 39025450, 2024). "We identified the histone methyltransferase KMT2D to be essential for GC-induced cell death in multiple lymphoma and multiple myeloma cells." (PMID 39025450, 2024). "Knockout of KMT2D by CRISPR/Cas9 gene editing in Jurkat and several multiple myeloma cell lines downregulated GR protein expression." (PMID 39025450, 2024).
non-Hodgkin lymphoma (3 papers, 2015 to 2024). Distinct from Hodgkin lymphoma both morphologically and biologically, non-Hodgkin lymphoma (NHL) is characterized by the absence of Reed-Sternberg cells, can occur at any age, and usually presents as a localized or generalized lymphadenopathy associated with fever and weight loss. "For instance, a recent report shows that a novel miRNA over-expressed in DLBCL (miR-10393-3p) is significantly anti-correlated with the expression of KMT2D and EP300, two genes that are involved in chromatin regulation and that are recurrently mutated in non-Hodgkin lymphoma (NHL)." (PMID 26404381, 2015).
squamous cell carcinoma (3 papers, 2021 to 2024). A carcinoma arising from squamous epithelial cells. "Mutations in KMT2D (MLL2), a closely related methyltransferase, have been identified in squamous cell carcinomas and reported in sebaceous carcinomas with a UV damage mutational signature." (PMID 34445161, 2021). "Mutations in the chromatin remodeling genes KMT2C and KMT2D were reported in cervical adeno‐ and squamous cell carcinomas (19% and 15%, respectively), but were absent in previously reported SCLCs and in the UCSCCs analyzed here." (PMID 33830625, 2022).